WDR46 (WD repeat domain 46)
Description:
Scaffold component of the nucleolar structure. Required for localization of DDX21 and NCL to the granular compartment of the nucleolus. Part of the small subunit (SSU) processome, first precursor of the small eukaryotic ribosomal subunit. During the assembly of the SSU processome in the nucleolus, many ribosome biogenesis factors, an RNA chaperone and ribosomal proteins associate with the nascent pre-rRNA and work in concert to generate RNA folding, modifications, rearrangements and cleavage as well as targeted degradation of pre-ribosomal RNA by the RNA exosome.
Synonyms: BING4; C6orf11; FP221; UTP7
Tractability: Small molecule: a structure with a bound ligand is known. PROTAC: ubiquitination databases record sites on it; its protein half-life has been measured.
Gene: Protein-coding gene on chromosome 6 (33,279,108 to 33,289,247, reverse strand). Ensembl gene ENSG00000227057.
Subcellular location: Nucleus, nucleolus
Subcellular location (Human Protein Atlas): Nucleoli
Pathways (Reactome):
Metabolism of RNA: Major pathway of rRNA processing in the nucleolus and cytosol; rRNA modification in the nucleus and cytosol
Gene Ontology:
Molecular function: RNA binding
Biological process: ribosomal small subunit biogenesis; maturation of SSU-rRNA; maturation of SSU-rRNA from tricistronic rRNA transcript (SSU-rRNA, 5.8S rRNA, LSU-rRNA)
Cellular component: nucleolus; small-subunit processome; nucleoplasm
Genetic constraint (gnomAD): Loss-of-function variants: 59 observed, 78.06 expected, observed/expected ratio (o/e) 0.76, 90% interval 0.61 to 0.94. The upper end of that interval is the gene's LOEUF score, 0.94, which puts it in group 3 of 6, group 1 being the genes least tolerant of losing a copy. Missense variants: 702 observed, 821.02 expected, observed/expected ratio (o/e) 0.86, 90% interval 0.8 to 0.91. Synonymous variants: 278 observed, 311.11 expected, observed/expected ratio (o/e) 0.89, 90% interval 0.81 to 0.99.
Homologues: Orthologues: chimpanzee WDR46 (99% identical), macaque WDR46 (97% identical), dog WDR46 (89% identical), pig WDR46 (88% identical), guinea pig WDR46 (86% identical), rat Wdr46 (86% identical), mouse Wdr46 (85% identical), tropical clawed frog wdr46 (51% identical), zebrafish wdr46 (51% identical), Drosophila melanogaster CG2260 (38% identical), Caenorhabditis elegans wdr-46 (37% identical).
Diseases named in the same sentence as WDR46 in open-access papers:
WDR46 is named in the same sentence as 4 diseases in open-access papers, as found by Europe PMC text mining. Sharing a sentence is not in itself a finding about the gene and the disease. The quoted sentences say what the papers report.
lymphoma (1 paper, 2022). A malignant (clonal) proliferation of B- lymphocytes or T- lymphocytes which involves the lymph nodes, bone marrow and/or extranodal sites. "The HPA database results showed that the protein levels of TSR1, WDR46, HSP90AA1, and NOP56 in lymphoma were higher than those in normal lymphoid tissue, whereas the protein level of UBC in lymphoma was lower than that in normal lymphoid tissue." (PMID 35263200, 2022).
tumor (2 papers, 2022 to 2024). "Upregulated genes include WDR46 and DDN, both of which are highly and specifically expressed in CNS NB-FOXR2 patient tumor tissues compared to the other subtypes." (PMID 39220247, 2024). "The expression levels of mRNA and proteins of TSR1, WDR46, HSP90AA1, and NOP56 in DLBCL were significantly higher than those in normal tissues, suggesting that these four hub genes can be activated and can upregulate the expression of mRNA during tumor development." (PMID 35263200, 2022).
respiratory disease (1 paper, 2013). "Another example is the G to A transition described in the WDR46 gene that originates an amino acid change from glycine to arginine at codon 18 of a uORF in the WDR46 transcript; this variant is associated with higher risk of aspirin-exacerbated respiratory disease." (PMID 23950723, 2013).
WDR46 also shares sentences with these, for which no sentence is quoted: diabetic retinopathy (1 paper).